ESYT1 (extended synaptotagmin 1)
Description:
Binds calcium (via the C2 domains) and translocates to sites of contact between the endoplasmic reticulum and the cell membrane in response to increased cytosolic calcium levels. Helps tether the endoplasmic reticulum to the cell membrane and promotes the formation of appositions between the endoplasmic reticulum and the cell membrane. Acts as an inhibitor of ADGRD1 G protein-coupled receptor activity in absence of cytosolic calcium. Binds glycerophospholipids in a barrel-like domain and may play a role in cellular lipid transport (By similarity).
Synonyms: FAM62A; KIAA0747; MBC2
Tractability: Antibody: UniProt places it where antibodies can reach, with high confidence; UniProt predicts a signal peptide or a membrane-spanning region; its Gene Ontology location is reachable by antibodies, with medium confidence. PROTAC: ubiquitination databases record sites on it; its protein half-life has been measured.
Gene: Protein-coding gene on chromosome 12 (56,118,250 to 56,144,674, forward strand). Ensembl gene ENSG00000139641.
Subcellular location: Endoplasmic reticulum membrane; Cell membrane
Subcellular location (Human Protein Atlas): Endoplasmic reticulum
Pathways (Reactome):
Signal Transduction: RAC1 GTPase cycle; RAC2 GTPase cycle; RAC3 GTPase cycle; RHOD GTPase cycle; RHOF GTPase cycle; RHOG GTPase cycle
Transport of small molecules: Glycosphingolipid transport
Gene Ontology:
Molecular function: identical protein binding; phospholipid transfer activity; protein binding; calcium ion binding; calcium-dependent phospholipid binding; phosphatidylcholine binding; phosphatidylethanolamine binding; phosphatidylinositol binding; lipid binding
Biological process: intermembrane lipid transfer; lipid transport; phospholipid transport
Cellular component: endoplasmic reticulum; endoplasmic reticulum membrane; membrane; plasma membrane
Genetic constraint (gnomAD): Loss-of-function variants: 116 observed, 161.25 expected, observed/expected ratio (o/e) 0.72, 90% interval 0.62 to 0.84. The upper end of that interval is the gene's LOEUF score, 0.84, which puts it in group 3 of 6, group 1 being the genes least tolerant of losing a copy. Missense variants: 1,264 observed, 1,449.7 expected, observed/expected ratio (o/e) 0.87, 90% interval 0.83 to 0.91. Synonymous variants: 500 observed, 570.61 expected, observed/expected ratio (o/e) 0.88, 90% interval 0.81 to 0.94.
Homologues: Orthologues: chimpanzee ESYT1 (99% identical), macaque ESYT1 (95% identical), rabbit ESYT1 (89% identical), guinea pig ESYT1 (88% identical), pig ESYT1 (88% identical), dog ESYT1 (88% identical), mouse Esyt1 (87% identical), rat Esyt1 (87% identical), tropical clawed frog esyt1 (53% identical), zebrafish esyt1b (45% identical), zebrafish esyt1a (45% identical), Drosophila melanogaster Esyt2 (23% identical). Paralogues in human: ESYT2 (34% identical), ESYT3 (29% identical).
Diseases named in the same sentence as ESYT1 in open-access papers:
ESYT1 is named in the same sentence as 12 diseases in open-access papers, as found by Europe PMC text mining. Sharing a sentence is not in itself a finding about the gene and the disease. The quoted sentences say what the papers report.
Sepsis (2 papers, 2024 to 2026). Sepsis is defined as life-threatening organ dysfunction caused by a dysregulated host response to infection. "A total of 1389 DEGs such as NOV, SEPT9, XIST, ESYT1 were upregulated in sepsis, whereas 1657 DEGs such as S100A9, IRAK3, MCEMP1, TLR5, CD177 were downregulated." (PMID 41542228, 2026).
osteoarthritis (1 paper, 2024). A noninflammatory degenerative joint disease occurring chiefly in older persons, characterized by degeneration of the articular cartilage, hypertrophy of bone at the margins and changes in the synovial membrane. "UGCG and ESYT1 were considered as hub LMRGs in the development of osteoarthritis, which were regarded as candidate diagnostic markers." (PMID 38637751, 2024). "UGCG and ESYT1, which are hub genes involved in lipid metabolism in osteoarthritis, were identified through the utilization of three machine learning algorithms." (PMID 38637751, 2024). "After synthesizing three machine learning algorithms, Lasso regression, SVM-RFE, and random forest, four hub genes of osteoarthritis lipid metabolism were further screened: UGCG, ESYT1, PTGS2, and CERK." (PMID 38637751, 2024). "Ultimately, 4 hub genes (UGCG, ESYT1, PTGS2, and CERK) were identified as vital players in osteoarthritis lipid metabolism." (PMID 38637751, 2024).
schizophrenia (1 paper, 2022). A major psychotic disorder characterized by abnormalities in the perception or expression of reality. "Finally, dysregulation of glutamatergic and serotoninergic genes, such as Grina, Htra1, and Tph2, has been reported in several NDs, and Esyt1 is increased in the brain from schizophrenia patients." (PMID 35268026, 2022).
cancer (4 papers, 2019 to 2024). A tumor composed of atypical neoplastic, often pleomorphic cells that invade other tissues. "Acting via E-Syt1 (Extended Synaptotagmin-1), the lipid transport protein, ANKRD22 stimulates lipid transport into mitochondria and reduces the number of mitochondria, thus further promoting the reprogramming of cancer cells to meet their metabolic requirements." (PMID 34769108, 2021).
tumor (3 papers, 2011 to 2024). "Three genes are relevant to this locus: RPL41, a ribosomal protein not considered to be related to the immune system; ZC3H10, a zinc finger protein related to tumour growth; and ESYT1, a synaptotagmin-like protein of unknown function." (PMID 21779181, 2011).
ESYT1 also shares sentences with these, for which no sentence is quoted: hepatocellular carcinoma (2 papers); liver cancer (2); Atrophy (1); colorectal cancer (1); metabolic disorders (1); non-small cell lung carcinoma (1); triple-negative breast carcinoma (1).